MC4R (melanocortin 4 receptor)
Diseases named in the same sentence as MC4R in open-access papers (continued):
Sharing a sentence is not in itself a finding about the gene and the disease.
Obesity (continued). "We describe the therapeutic journey of a 33-year-old patient with early-onset obesity (BMI 56.7 kg/m2) and hyperphagia due to a likely pathogenic heterozygous melanocortin-4 receptor (MC4R) gene variant." (PMID 36876127, 2023). "MC4R rs17782313 significantly interacted with several eating behaviors to enhance the risk of obesity." (PMID 38002939, 2023). "More than 300 mutations in human MC4R have been identified from patients, and MC4R mutations are considered to be the leading cause of monogenic obesity." (PMID 37627313, 2023). "Mutations in the MC4R gene are a leading cause of monogenic forms of obesity, and MC4R variants have been linked to increased obesity in certain populations." (PMID 37443835, 2023). "For example, administration of MC4R antagonists or the knockout of the MC4R gene in rodents resulted in an increase in feeding behavior, obesity, and linear growth, the opposite of what is seen with loss of MC3R function." (PMID 36910260, 2023). "At the physiological phenotype level, CRISPRa has also been used to increase the transcription of obesity risk genes SIM1 and MC4R, and to successfully rescue haploinsufficient obesity in mouse models—with the effects persisting up to 9 months post-treatment." (PMID 36792602, 2023). "Here, we describe the remarkable therapeutic journey of anti-obesity treatments for a patient with severe obesity and hyperphagia due to a heterozygous MC4R deficiency." (PMID 36876127, 2023). "MC4R deficiency is the most common cause of monogenic obesity and is typically characterized by obesity, increased bone mineral density, increased linear growth in early childhood, hyperphagia, and severe hyperinsulinemia." (PMID 37374323, 2023). "In contrast, for anorexigenic POMC and MC4R neurons, animal models with loss of function develop obesity while those of gain of function have a limited impact on body weight." (PMID 37069175, 2023). "Monogenic obesity is a type of rare and severe early-onset obesity, resulting from a single mutation of a gene such as MC4R, LEP, LEPR, and POMC primarily involved in the leptin–melanocortin pathway." (PMID 37327085, 2023). "The summation of these genetic mutations leads to an overall decrease in MC4R function, thus leading to obesity." (PMID 37937009, 2023). "While mutations in the melanocortin-4 receptor (MC4R) gene is the most common cause of obesity caused by mutations in a single gene, the link between MC4R function and vascular disease has still remained unclear." (PMID 37957201, 2023). "The prevalence of obesity (BMI >30 kg/m2) among carriers of DMG variants in MC4R was 39% (228 of 591) in females and 38% (195 of 518) in males, with ORs of 2.01 [1.68–2.41] and 1.71 [1.41–2.08], respectively." (PMID 37601970, 2023). "Receptor dimerization has been reported for human MC4R, and MC4R mutations which have impaired the dimerization are obesity-associated." (PMID 38027153, 2023). "Our study suggests that the C–C–C haplotype of the SNPs rs17782313, rs17773430 and rs34114122 of the MC4R gene potentiates metabolic risk factors at early ages in children with obesity." (PMID 37508717, 2023). "Patients carrying disease-causing variants in the MC4R gene are characterized by extreme obesity, hyperphagia, and increased linear growth." (PMID 38003551, 2023). "While these studies provide some evidence for sex-specific effects, more research is needed to establish a definitive link between MC4R rs17782313 and sex-specific obesity risk." (PMID 38002939, 2023). "Patients with heterozygous MC4R variants are more common than homozygous or compound heterozygous carriers, where the latter develop a more severe form of obesity." (PMID 38003551, 2023). "Pathogenic variants in the MC4R gene have been shown to cause MC4R deficiency, one of the most common types of monogenic obesity." (PMID 36876127, 2023). "We aimed to study the association of MC4R rs177823313 with obesity risk and eating habits in the Israeli population." (PMID 38002939, 2023).
Obesity (continued). "Both genes have previously been linked to obesity, and it is noteworthy that MC4R is involved in appetite regulation." (PMID 38035352, 2023). "There was interaction between high energy intake and MC4R polymorphism in determining the risk of obesity after adjusting for confounders such as age, gender and physical activity (OR = 1.39, p = 0.01)." (PMID 36123585, 2022). "A mutation in the gene encoding the melanocortin 4 receptor (MC4-R) causing it to be defective in humans is one of the most common causes of obesity, glucose intolerance and T2DM." (PMID 36248900, 2022). "Approximately 5% of severe obesity cases are associated with loss of function mutations in the hypothalamic appetite-regulating melanocortin-4 receptor (MC4R), the most common cause of monogenic non-syndromic obesity." (PMID 36553534, 2022). "A melanocortin-4 receptor gene homozygous mutation exhibited morbid early-onset obesity, and a heterozygote individual also had the possibility to have a milder overweight on mice." (PMID 35625377, 2022). "The most common type of monogenetic obesity is linked to melanocortin-4 receptor (MC4R) deficiency, which was identified in 2–5% of obese patients." (PMID 36362948, 2022). "Intriguingly, a recent study demonstrates that the β-arrestin-biased MC4R variants are associated with a lower risk of obesity in humans, suggesting that MC4R plays a key role in regulating body weight through β-arrestin signaling." (PMID 35741395, 2022). "Obesity due to melanocortin-4 receptor deficiency, the most common genetic cause of human obesity, also reduces T-cell repertoire diversity." (PMID 36685567, 2022). "We and others have shown that SG is not effective in maintaining weight loss in early-onset genetic obesity modeled by db/db mice or Melanocortin 4 Receptor null rats, yet it is effective in obesity models induced through a calorie-rich diet." (PMID 36033613, 2022). "Previous studies, however, have assessed the interaction between the DASH diet and some genes, such as genetic predisposition to obesity, based on BMI-associated variants, as well as MC4R rs17782313 polymorphism on cardiometabolic risk factors." (PMID 35585604, 2022). "Mutations in the Melanocortin-4-receptor (MC4R) gene is the most prevalent monogenic cause of obesity, with a prevalence of 1.7–3.0% among obese people." (PMID 35538513, 2022). "Though evidence on the relation of MC4R SNP to energy expenditure is partial in humans, we found that its mutated variants are associated with indices of obesity and decreased energy expenditure by having an interaction with dietary carbohydrate intake." (PMID 35538513, 2022). "Mutation in the MC4R is one of the most common causes of non-syndromic monogenic obesity in humans, with a prevalence of around 4%." (PMID 35447963, 2022). "As previously reported in other Mexican cohorts, the MC4R Ile269Asn mutation was associated with adult obesity in the present study." (PMID 36553534, 2022). "A subsequent stratification analysis illustrated the differed association between MC4R gene and obesity in Yi farmers and Yi rural-to-urban migrants." (PMID 35495128, 2022). "The association of MC4R variants with obesity have been replicated in Chinese, but the evidence in ethnic minorities was limited." (PMID 35495128, 2022). "It has been previously shown that MC4R play certain biological functions in obesity, and they are also associated with breast cancer, colon cancer and endometrial cancer." (PMID 34787056, 2022). "MC4R gene plays an essential role in the central control of energy homeostasis and development of obesity-associated metabolic diseases." (PMID 36440355, 2022). "Many studies have reported the association between MC4R variants and obesity, especially rs17782313." (PMID 36123585, 2022).
Obesity (continued). "The etiology of obesity in AHO is not well known but different theories exist including mutations in MC4R, which is transduced by Gsα, and mediated anorexigenic signals from hormones and other neurotransmitters." (PMID 36232301, 2022). "Considering the most well-known associations between obesity and strokes, we aimed to assess the potential genetic roles of the MC4R and the FTO in populations susceptible to stroke." (PMID 36530622, 2022). "This was the first study that assessed the interaction between MC4R rs17782313 variant and stress, anxiety, depression, and stress hormone (cortisol) affects obesity risk." (PMID 36123585, 2022). "Several studies have shown a significant association between the FTO rs9930506 and MC4R rs17782313 polymorphisms and obesity in children." (PMID 36499740, 2022). "MC4R-deficient mice show an earlier onset of hyperphagia and obesity associated with hyperinsulinemia than 5-HT2CR-deficient mice." (PMID 35163521, 2022). "MC4R inactivation in mice also caused obesity, hyperphagia and hyperglucemia, suggesting that MC4R is one of the most common obesity-related genes." (PMID 33826123, 2022). "The polymorphisms in the FTO and the MC4R were linked to overweight or obesity in children and adolescents." (PMID 36530622, 2022). "MC4R is reported to play a significant role in energy balance and weight control, and inherited MC4R variant is one of the causes of obesity." (PMID 36034923, 2022). "Efforts of genetic studies to find the genes involved in the energy balance have led to detection of several obesity-related genes including the leptin, melanocortin-4 receptor (MC4R), and fat mass and obesity-associated (FTO)." (PMID 36440355, 2022). "A study conducted on Maonan people in Guangxi Province examined the association of the MC4R gene with obesity, and the results showed that rs17782313 and rs476828 of the three SNPs were related to obesity." (PMID 35495128, 2022). "The loss of function melanocortin 4-receptor (MC4R) Ile269Asn mutation has been proposed as one of the most important genetic contributors to obesity in the Mexican population." (PMID 36553534, 2022). "These phenotypes overlap with those seen in humans (and mice) with loss-of-function mutations in MC4R, which represent the commonest monogenic cause of obesity." (PMID 36175420, 2022). "The long-term follow-up data on this very unique genetic setting show that weight loss and amelioration of obesity following bariatric surgery require active MC4R signaling, while the improvement in glycemia is in part independent of weight loss." (PMID 35629934, 2022). "FTO rs9939609 and MC4R rs17782313 polymorphisms have been associated with overweight and obesity in children." (PMID 36499740, 2022). "MC4R gene polymorphisms positively interacted with rural-to-urban migration on obesity in Yi people." (PMID 35495128, 2022). "Even with melanocortin-4 receptor deficiency, which causes obesity, the rate of obesity differs among generations." (PMID 36291357, 2022). "Variable phenotype–genotype concordance is also known in other monogenic causes of obesity, for example MC4R mutations." (PMID 36536132, 2022). "All these genes are strongly associated with body mass index and obesity risk, related mechanisms involving regulation of cell migration, and the defects in MC4R were a cause of autosomal dominant obesity." (PMID 36185695, 2022). "In another fMRI study, patients with obesity and MC4R deficiency had a high striatal (dorsal and ventral striatum) activity to palatable foods in the sated state compared with non-carrier with obesity." (PMID 35447963, 2022). "A number of mutations have been reported in MC4R that are responsible for causing obesity and related complications." (PMID 35807283, 2022). "To date, most studies exploring the association of MC4R rs17782313 with risk of obesity and insulin resistance, high BMI and large waist circumference demonstrate an influence of the C allele." (PMID 35292917, 2022).
Obesity (continued). "It has been reported that loss‐of‐function mutations in the coding sequence of MC4R gene increases the predisposition to obesity." (PMID 34672391, 2022). "This mutation was formerly associated with childhood and adult obesity in Mexico, and in vitro studies showed that it results in complete loss of function of the MC4R protein." (PMID 36553534, 2022). "MC4R mutations are closely associated with obesity in humans, and about 1%–2.5% people with severe obesity contain a pathogenic MC4R mutation." (PMID 33826123, 2022). "With a population-based case–control design, this study confirmed the association between MC4R gene polymorphism and obesity as well as the interaction with rural-to-urban living environment transformation in Yi people." (PMID 35495128, 2022). "Often FTO variants have been investigated with variants in the MC4R of which mutations can be positioned between monogenic obesity and the polygenic obesity." (PMID 36452324, 2022). "In the case–control association study, 5/483 normal weight individuals (1%) and 45/1200 individuals with obesity (3.8%) were heterozygous for the MC4R Ile269Asn mutation." (PMID 36553534, 2022). "MC4R mutations compromise 3%–5% of cases of monogenic obesity in humans, making MC4R signaling and its downstream circuitry an appealing target for obesity therapeutics." (PMID 36568981, 2022). "The activation of MC4R results in the inhibition of food intake, while loss of MC4R function in humans and rodents leads to obesity, insulin resistance, and diabetes." (PMID 35571924, 2022). "Heterozygous mutations in MC4R alone, however, are implicated in 6% of early-onset severe obesity in the adult population alone." (PMID 35807283, 2022). "This cross-sectional study investigated the relationship of genetic risk score by obesity-related genetic markers, including MC4R (rs17782313), CAV-1 (rs3807992), and Cry-1 (rs2287161), with cardiometabolic risk factors in overweight and obese women." (PMID 36324080, 2022). "As strength points, to the best of our knowledge, this is the first study to identify an interaction between dietary carbohydrate and MC4R rs17782313 for the susceptibility to increased measures of central and general obesity as well as metabolic rate." (PMID 35538513, 2022). "In this sense, the variant rs17782313 near the MC4R gene has been strongly linked with obesity and showed a significant association with dietary intake, total energy intake, increased snacking, as well as hunger." (PMID 36123585, 2022). "This study was designed to identify the association of MC4R gene polymorphisms (rs17782313 and rs12970134) with obesity in Yi people and to explore the effect of gene–environment interaction on obesity." (PMID 35495128, 2022). "Mutations in the MC4R account for up to 5% of obesity cases and are the most frequent monogenic cause for obesity." (PMID 36009013, 2022). "The MC4R is a key player in energy homeostasis and satiety regulation, and MC4R deficiency is the most common cause of monogenetic obesity." (PMID 36362948, 2022). "The association between the SNPs near the MC4R gene and obesity was first reported in European populations and has subsequently been verified in Finland and France, Denmark, Japan, and other different areas." (PMID 35495128, 2022). "MC4R localizes to primary cilia of MC4R neurons, and obesity-associated mutations impair its ciliary localization." (PMID 36561368, 2022). "The FTO gene is known to be firmly associated with higher body mass index and obesity risk, while the MC4R gene is the most common causative gene of monogenic obesity." (PMID 35845810, 2022). "Among these loci were MC4R (melanocortin-4 receptor), an obesity-associated gene, and TEK (TEK receptor tyrosine kinase, rs78411354), which plays a role in embryonic vascular development." (PMID 36240095, 2022).
Obesity (continued). "Among numerous genes associated with human obesity, the MC4R has proved to be particularly significant, by controlling appetite and playing a crucial role in the regulation of energy homeostasis, glucose metabolism, and body weight." (PMID 35571924, 2022). "We have shown that the obesity-protective alleles (MC4R T and PPARG C) were positively associated with weight loss efficiency." (PMID 35292917, 2022). "The new drug, Setmelanotide, is an eight-amino acid cyclic peptide labeled as BIM-22493 or RM-493 that functions as an MC4R agonist to treat the monogenic causes of obesity caused by POMC deficiency by lowering food intake and restoring insulin sensitivity." (PMID 36012526, 2022). "Fat Mass and Obesity-Associated (FTO) and the Melanocortin-4 Receptor (MC4R) genes are strongly associated with obesity, an established risk factor for stroke." (PMID 36530622, 2022). "Evidence suggests that MC4R polymorphism (rs17782313) is an important genetic factor in obesity that disrupts energy homeostasis." (PMID 36123585, 2022). "In this sense, variants in the rs17782313 near the MC4R have been strongly related to obesity and showed a significant association with the dietary intake, total energy intake, increased snacking, as well as hunger." (PMID 35538513, 2022). "Experimental studies showed that loss of MC4R function is associated with overeating, hyperinsulinemia, and obesity." (PMID 36123585, 2022). "About 20% of single-nucleotide variants in the MC4R gene have been projected to be pathogenic or likely pathogenic, emphasizing MC4R's prevalence in monogenic obesity." (PMID 36225863, 2022). "Approximately 2% to 5% of individuals with childhood obesity have heterozygous mutations in the MC4R gene, making it the most common gene for which highly penetrant variants contribute to obesity." (PMID 36499740, 2022). "Several SNPs in MC4R have been correlated with obesity since the protein encoded by it plays a vital role in weight control, energy balance, and food intake." (PMID 36532520, 2022). "This study represents a proof-of-principle for pharmacoperone application as a therapeutic strategy for severe obesity associated with mutations in the MC4R." (PMID 36093106, 2022). "It remains, however, to explore the effect of MC4R rs17782313 polymorphism on the association of dietary carbohydrate quantity and quality with obesity and energy expenditure." (PMID 35538513, 2022). "We found that obesity-linked MC4R variants, such as MC4RI317T, have decreased expression at the cell surface of Neuro2A cells because they are retained as misfolded proteins in the ER and they induce ER stress." (PMID 36614074, 2022). "Statistical and biological interactions with MD modulate the effects of FTO and MC4R polymorphisms on obesity." (PMID 35327974, 2022). "They analyzed the five obesity-associated genetic variants (MC4R rs17782313, BDNF rs6265, FTO rs1421085, TMEM18 rs7561317, and NEGR1 rs2815752)." (PMID 35627568, 2022). "Additional clinically relevant variants or CNVs in genes related to obesity, such as MC4R, POMC and LEPR, were excluded by exome sequencing and a TruSight One Sequencing panel." (PMID 36536132, 2022). "Pomc and Mc4r deficiency in rodents and humans causes early onset of obesity, whereas a loss of Agrp function is associated with leanness." (PMID 35474338, 2022). "A limited number of studies have examined the association between MC4R rs17782313 polymorphism and obesity-related behaviors as well as the interaction of these factors with MC4R rs17782313 on obesity." (PMID 36123585, 2022). "Mutations in the MC4R gene is the most prevalent monogenic cause of obesity, with a prevalence of 1.7–3.0% among obese people." (PMID 36123585, 2022). "Considering that previous studies have identified this polymorphism as the most significant MC4R polymorphism associated with obesity, the research focused only on obese and overweight individuals." (PMID 36123585, 2022).